Y_RNA (Y RNA )
Gene: Miscellaneous RNA gene on chromosome 7 (40,128,121 to 40,128,232, reverse strand). Ensembl gene ENSG00000199273.
Homologues: Orthologues: chimpanzee Y_RNA (96% identical), macaque Y_RNA (84% identical), dog Y_RNA (79% identical). Paralogues in human: RNY1 (88% identical), Y_RNA (87% identical), RNY1P11 (86% identical), Y_RNA (86% identical), Y_RNA (85% identical), Y_RNA (84% identical), RNY1P8 (83% identical), Y_RNA (83% identical), Y_RNA (82% identical), RNY1P5 (81% identical), Y_RNA (81% identical), RNY1P10 (80% identical), and 95 more.